BLACAT1 (BLACAT1 overlapping LEMD1 locus)
Synonyms: linc-UBC1; LINC00912; onco-lncRNA-30
Gene: Protein-coding gene on chromosome 1 (205,434,885 to 205,457,390, reverse strand). Ensembl gene ENSG00000281406.
Diseases named in the same sentence as BLACAT1 in open-access papers:
BLACAT1 is named in the same sentence as 31 diseases in open-access papers, as found by Europe PMC text mining. Sharing a sentence is not in itself a finding about the gene and the disease. The quoted sentences say what the papers report.
breast cancer (11 papers, 2018 to 2025). A primary or metastatic malignant neoplasm involving the breast. "Upregulated lncRNA BLACAT1 was linked with aggressive breast cancer phenotype by lncRNA BLACAT1/miR-150-5p/CCR2 (C-C chemokine receptor type 2) axis." (PMID 36685962, 2022). "Further clinical analysis showed that higher BLACAT1 expression in breast cancer tissues was associated with metastasis and tumor staging." (PMID 30733855, 2019). "Furthermore, elevated expression of BLACAT1 was associated with metastasis and higher tumor staging in breast cancer tissues and its downregulation decreased cell migration in SKBR3 and MDA-MB-231 cells with miR-150-5p overexpression." (PMID 36939965, 2023). "Recent research reveal that miR-503 can directly bind to and inhibit BLACAT1 (bladder cancer-associated transcript 1), a long non-coding RNA associated with developing chemotherapy resistance in T47D and MCF7 breast cancer cells." (PMID 41283333, 2025). "For instance, an oncogenic lncRNA BLACAT1 was reported in osteosarcoma (OS), pancreatic cancer (PC), breast cancer (BC), and CRC." (PMID 36064442, 2022). "In the study, we found that the expression of BLACAT1 in breast cancer tissue/cells was increased, and its expression levels were related to the breast cancer metastasis, staging and survival." (PMID 30733855, 2019). "The data indicated that BLACAT1 down-regulation suppressed breast cancer cell growth by sponging miR-150-5p." (PMID 30733855, 2019). "In conclusion, above evidence reveals the vital role of lncRNA BLACAT1 in the growth and metastasis of breast cancer." (PMID 30733855, 2019). "In this study, it is aimed to explore the roles and molecular mechanisms of BLACAT1 in breast cancer." (PMID 30733855, 2019). "The data indicated that BLACAT1 promoted breast cancer cell proliferation and metastasis by miR-150-5p/CCR2." (PMID 30733855, 2019). "The data indicated that BLACAT1 down-regulation suppressed breast cancer cell metastasis by sponging miR-150-5p." (PMID 30733855, 2019). "Our results reveal that BLACAT1 promoted CCR2 expression on post-transcriptional levels through sponging miR-150-5p in breast cancer." (PMID 30733855, 2019). "The molecular mechanism experiments demonstrated that BLACAT1 down-regulation suppressed the proliferation and metastasis of human breast cancer cells by regulating miR-150-5p targeting CCR2." (PMID 30733855, 2019). "It was shown that BLACAT1 levels were higher in breast cancer tissues than their compared normal tissues." (PMID 30733855, 2019). "Lnc015192 regulates miR-34a and subsequently targets Adam12 in breast cancer through a ceRNA mechanism, and studies have also shown that LncRNA BLACAT1 promotes glioma development by binding to miR-605-3p to regulate VASP expression and promote glioma development and progression." (PMID 36943627, 2023). "The survival time was shorter in breast cancer patients with high BLACAT1 expression." (PMID 30733855, 2019). "Our team investigated the potential regulatory pathway of BLACAT1 in breast cancer cells." (PMID 30733855, 2019). "The data suggested that BLACAT1 maybe function as a tumor promoting long non-coding RNA in breast cancer." (PMID 30733855, 2019). "However, if the BLACAT1 would be a prognostic maker, BLACAT1 levels in circulation will be detected in the breast cancer patients." (PMID 30733855, 2019). "In this study, we evaluated the regulatory roles of BLACAT1 in breast cancer." (PMID 30733855, 2019). "We found BLACAT1 took part in breast cancer cell aggressive phenotype." (PMID 30733855, 2019). "For instance, lncRNA BLACAT1 could function as a non-specific diagnostic and prognostic biomarker for multiple cancers, including hepatocellular cancer, lung cancer, and breast cancer, due to its upregulated expression level in these cancers." (PMID 37037818, 2023). "The results indicated that miR-150-5p might be a sponge of BLACAT1 in breast cancer cells." (PMID 30733855, 2019).
breast cancer (continued). "However, the regulatory and molecular mechanism of BLACAT1 in breast cancer are still unclear." (PMID 30733855, 2019). "Further data analysis showed that BLACAT1 was negatively related to miR-150-5p expression and positively related to CCR2 mRNA levels in breast cancer tissues." (PMID 30733855, 2019). "The research verified the involvement of BLACAT1 in accelerating cell survival and metastasis through miR-150-5p targeting CCR2 in breast cancer cells." (PMID 30733855, 2019). "For exploring the regulatory roles of BLACAT1 in breast cancer cells, firstly, BLACAT1 expression was measured in MCF10A cells and seven breast cancer cell lines including MCF-7, BT474, SKBR3, SUM149, MDA-MB-231, MDA-MB-435 and MDA-MB-468." (PMID 30733855, 2019). "Here, the relationship between BLACAT1, miR-150-5p and CCR2 expression in breast cancer was analyzed." (PMID 30733855, 2019). "BLACAT1 promotes human breast cancer tumorigenesis by targeting miR-150-5p/CCR2 axis, suggesting the novel molecular mechanism of breast cancer." (PMID 30733855, 2019). "Reduced expression of BLACAT1 in HNSCC; MALAT1, NEAT1 and PVT1 in NPC; FAM201A, PVT1 and LINC00857 in NSCLC; LINC00473, CCAT2and Rpph1 in EC; HOTAIR and LINC00958 in CRC; AFAP1-AS1 and LINC00511 in breast cancer were correlated with radiosensitivity." (PMID 36323697, 2022). "BLACAT1 is one of lncRNA and the roles of it in breast cancer is not clear." (PMID 30733855, 2019).
colorectal cancer (9 papers, 2017 to 2024). A primary or metastatic malignant neoplasm that affects the colon or rectum. "BLACAT1 also affects cell proliferation, indicates a prognosis of colorectal cancer and is significantly associated with poor overall survival." (PMID 30453959, 2018). "Many evolving studies revealed that BLACAT1 was abnormally expressed in different cancers, including colorectal cancer (CRC), gastric cancer (GC), and lung cancer (LC)." (PMID 36939965, 2023). "Numerous studies reported the upregulation of BLACAT1 in the tissue of many types of cancer, such as hepatocellular carcinoma, colorectal cancer, glioma, and osteosarcoma." (PMID 36939965, 2023). "Currently, lncRNA BLACAT1 have been confirmed as a dysregulated oncogene in other several malignancies, e.g., lung cancer, colorectal cancer, gastric cancer, papillary thyroid cancer, esophageal squamous cell carcinoma, and cervical cancer." (PMID 31061820, 2019). "A previous study has been reported that up-regulation of lncRNA BLACAT1 expression in bladder cancer, gastric cancer and colorectal cancer is a poor prognostic factor." (PMID 29599647, 2018). "We researched the correlation between PRC2 and BLACAT1 by RNA immunoprecipitation (RIP) in colorectal cancer cells, then we observed that endogenous BLACAT1 was significantly enriched in the anti-EZH2 RNA-IP fraction." (PMID 28277544, 2017). "For instance, long noncoding RNA BLACAT1 indicates a poor prognosis of colorectal cancer and affects cell proliferation by epigenetically silencing of p15." (PMID 29340086, 2017). "Our experiments showed that increased BLACAT1 was an independent unfavorable prognostic indicator for colorectal cancer, and revealed that BLACAT1 knockdown significantly repressed proliferation, both in vitro and in vivo." (PMID 28277544, 2017). "In this study, BLACAT1 expression of tumors infiltration confined within the mucosal layer (so-called early colorectal cancer) was compared with that of tumor infiltration beyond the mucosal layer." (PMID 28277544, 2017). "In colorectal cancer, incRNA BLACAT1 can repress p15 expression by binding to PRC2 (EZH2 part), thus contributing to the regulation of CRC cell cycle and proliferation." (PMID 29254174, 2017). "However, studies have indicated that lncRNA BLACAT1 is also overexpressed in other cancers, e.g., gastric cancer, small-cell lung cancer, and colorectal cancer." (PMID 31061820, 2019). "Importantly, we first reported that BLACAT1 serving as a member of PRC2-mediated epigenetic regulation participated in the development of colorectal cancer." (PMID 28277544, 2017). "Some studies have reported that MEG3 9, lnc-ATB 10 and BLACAT1 11 were up-expressed in colorectal cancer plasma, while NKILA 7 and HOTAIRM1 12 were down-regulated in colorectal cancer tissue." (PMID 32742499, 2020). "Moreover, BLACAT1 could regulate colorectal cancer cells proliferation both in vitro and in vivo." (PMID 28277544, 2017). "In our research, we illustrated high abundance binding between BLACAT1 and EZH2 in colorectal cancer cells, and we further confirmed that BLACAT1 could mediate epigenetic regulation of p15." (PMID 28277544, 2017).
gastric cancer (9 papers, 2017 to 2025). A primary or metastatic malignant neoplasm involving the stomach. "A high expression level of BLACAT1 is associated with oxaliplatin resistance in gastric cancer cells." (PMID 40352931, 2025). "Bladder cancer-associated transcript-1 (BLACAT1) is observed in resistant gastric cancer cells." (PMID 40352931, 2025). "The expression of BLACAT1 is increased in some cancers, such as medulloblastoma, colon adenocarcinoma, pancreatic adenocarcinoma, gastric cancer, and TC." (PMID 34335744, 2021). "Until now, BLACAT1, firstly characterized in bladder cancer, was also described to be involved in the development of gastric cancer." (PMID 28611953, 2017). "In vitro and in vivo studies observed that knockdown of BLACAT1 downregulates the expression of ABCB1 protein and inhibits the proliferation of gastric cancer cells." (PMID 40352931, 2025).
bladder cancer (7 papers, 2017 to 2023). "The lncRNA BLACAT1 (Bladder Cancer Associated Transcript 1) was up-regulated in bladder cancer." (PMID 30453959, 2018). "LncRNA bladder cancer-associated transcript 1 (BLACAT1, also known as linc-UBC1), located at 1q32.1 and with a length of 2616 bp, was initially identified and characterized in bladder cancer." (PMID 33371204, 2020). "LncRNA bladder cancer-associated transcript 1 (BLACAT1, also named as linc-UBC1), on the locus of human chromosome 1q32.1, was initially identified in bladder cancer." (PMID 31061820, 2019). "Initially, lncRNA BLACAT1 was identified as a frequently overexpressed oncogene in bladder cancer tissues." (PMID 31061820, 2019). "In conclusion, we can conclude that BLACAT1 may be considered one of the promising non-invasive metastatic biomarker for bladder cancer." (PMID 36939965, 2023). "So, urinary lncRNA BLACAT1 in the current study may be considered a unique metastatic biomarker and can be used to differentiate between invasive and non-invasive bladder cancer stages." (PMID 36939965, 2023).
cervical cancer (5 papers, 2019 to 2023). A primary or metastatic malignant neoplasm involving the cervix. "Depletion of BLACAT1 negatively affected cell proliferation, invasion, and migration in cervical cancer ME180 and C33A cells." (PMID 36939965, 2023). "Other lncRNAs, for example, Bladder cancer-associated transcript 1 (BLACAT1), and Taurine upregulated 1 (TUG1), also supports cervical cancer by altering β-catenin and modulating the Wnt signaling pathway." (PMID 32758292, 2020). "For example, in cervical cancer, the lncRNA BLACAT1 promotes proliferation, migration and invasion by modulating this pathway." (PMID 30499165, 2019). "Likewise, lncRNAs, such as BLACAT1, LINC00675 and TUG1, promoted the cervical cancer progression by activating Wnt/β-catenin signaling pathway." (PMID 31255182, 2019).
hepatocellular carcinoma (5 papers, 2020 to 2025). A malignant tumor that arises from hepatocytes. "RBMX serves as therapeutic target for hepatocellular carcinoma, because it promotes hepatocellular carcinoma development and reduce sorafenib sensitivity by targeting BLACAT1." (PMID 37194014, 2023). "In hepatocellular carcinoma (HCC) and T-cell lymphoma, elevated RBMX expression enhances tumor progression and chemoresistance by stabilizing oncogenic long non-coding RNAs (lncRNAs), such as BLACAT1, or modulating RNA metabolism." (PMID 40692788, 2025).
lung carcinoma (5 papers, 2018 to 2023). "Both lncRNA X‐inactive‐specific transcript (XIST) and bladder cancer‐associated transcript 1 (BLACAT1) can bind to miR‐17 and target autophagy‐related 7 (ATG7) to promote autophagy and reduce the chemosensitivity of lung cancer cells." (PMID 33931980, 2021). "Our team and other researchers have reported that AFAP1‐AS1 19 and BLACAT1 16 were significantly upregulated and play important roles in lung cancer." (PMID 29632808, 2018).
osteosarcoma (5 papers, 2022 to 2024). A usually aggressive malignant bone-forming mesenchymal neoplasm, predominantly affecting adolescents and young adults. "In individuals with osteosarcoma, a poor prognosis was suggested by the amplified expression of bladder cancer-associated transcript 1 (BLACAT1)." (PMID 39015175, 2024). "lncRNA BLACAT1 (Bladder cancer associated transcript 1) interacts with STAT3 and regulates the phosphorylation of STAT3 and contributes to the proliferation and migration of osteosarcoma cells." (PMID 35755302, 2022).
glioma (4 papers, 2022 to 2023). A benign or malignant brain and spinal cord tumor that arises from glial cells (astrocytes, oligodendrocytes, ependymal cells). "In addition, many lncRNAs, including PTCSC3, NEAT1, and BLACAT1, have been reported to regulate Wnt/β-catenin signaling pathway to affect glioma cell growth, migration, and invasion." (PMID 34923953, 2022).
non-small cell lung carcinoma (4 papers, 2019 to 2025). A group of at least three distinct histological types of lung cancer, including non-small cell squamous cell carcinoma, adenocarcinoma, and large cell carcinoma. "Furthermore, long non-coding RNA BLACAT1 inhibits cell proliferation in prostate cancer by acting on hsa-miR-361; long non-coding RNA PVT1 contributes to cell growth and metastasis in non-small-cell lung cancer by regulating miR-361-3p." (PMID 34948403, 2021).
lymph node metastasis (3 papers, 2018 to 2024). "Multivariate analysis showed that BLACAT1 was an independent risk factor for lymph node metastasis and gender (P < 0.05)." (PMID 29599647, 2018). "We also found that low plasma BLACAT1 expression was correlated with lymph node metastasis (LNM) (P < 0.001)." (PMID 29599647, 2018). "Furthermore, 7 studies represented the relationship between lncRNA BLACAT1 expression and clinicopathological features, including age, gender, smoking, TNM stage, tumor grade, lymph node metastasis (LNM), and distant metastasis (DM)." (PMID 31061820, 2019).
pancreatic cancer (3 papers, 2020 to 2025). "BLACAT1 inhibits the trimethylation of H3K27 on the CDKN1C gene by blocking the recruitment of EZH2, thereby promoting the expression of CDKN1C and inhibiting the expression of CCNE, and thus suppressing the biological processes of pancreatic cancer cells." (PMID 40778223, 2025).
papillary thyroid cancer (2 papers, 2018 to 2019). "However, the plasma expression of lncRNA BLACAT1 and its clinical value in patients with papillary thyroid cancer (PTC) remain unknown." (PMID 29599647, 2018).
prostate carcinoma (2 papers, 2021 to 2022). A carcinoma that arises from epithelial cells of the prostate gland. "Elevated expression of lncRNA BLACAT1 is correlated with pro-malignant features of cancer and lower survival time in patients with prostate cancer." (PMID 36483915, 2022).
colon cancer (1 paper, 2017). "Our results suggest that BLACAT1, as a cell cycle regulator, may serve as a potential target for colon cancer prevention and treatment in human CRC." (PMID 28277544, 2017). "One of them, BLACAT1, a cancer-associated long noncoding RNA, exerts regulatory functions in various biological processes in cancer cells, however, the role of BLACAT1 in colon cancer remains unclear." (PMID 28277544, 2017).
esophageal cancer (1 paper, 2024). A primary or metastatic malignant neoplasm involving the esophagus. "Also, BLACAT1 promotes the growth, expansion, and metastasis of esophageal cancer cells by competing with PD-L1 to bind to miR-5590-3p in these cells." (PMID 38462628, 2024).
head and neck squamous cell carcinoma (1 paper, 2020). A squamous cell carcinoma that arises from any of the following anatomic sites: lip and oral cavity, nasal cavity, paranasal sinuses, pharynx, larynx, and salivary glands. "Knockdown of lncRNA bladder cancer associated transcript 1 (BLACAT1) accelerated apoptosis of head and neck squamous cell carcinoma cells (HNSCC) by positively regulating expression of presenilin 1 protein (PSEN1)." (PMID 32585857, 2020).
nodular goiter (1 paper, 2018). Goiter characterized by discrete tissue mass(es) that may or may not produce thyroid hormones. "The diagnostic value of BLACAT1 on nodular goiter and PTC was evaluated by ROC curve." (PMID 29599647, 2018). "In this study, we found that the plasma expression of lncRNA BLACAT1 was significantly lower in PTC patients than that in patients with nodular goiter." (PMID 29599647, 2018). "The expression profile of BLACAT1 in 87 PTC patients (case group) and 36 patients with nodular goiter (control group) were investigated by qRT-PCR." (PMID 29599647, 2018).
osteoarthritis (1 paper, 2022). A noninflammatory degenerative joint disease occurring chiefly in older persons, characterized by degeneration of the articular cartilage, hypertrophy of bone at the margins and changes in the synovial membrane. "The lncRNA BLACAT1 regulates the differentiation of bone marrow stromal stem cells by targeting miR-142-5p in osteoarthritis." (PMID 35967352, 2022).
ovarian carcinoma (1 paper, 2021). A malignant neoplasm originating from the surface ovarian epithelium. "LncRNA BLACAT1 knockdown inhibited the ovarian cancer progression via suppressing the Wnt/β-catenin signaling pathway by sponging miR-519b-3p." (PMID 34116704, 2021).
uterine corpus endometrial carcinoma (1 paper, 2017). A endometrial carcinoma (disease) that involves the body of uterus. "Surprisingly, Kaplan-Meier survival analysis revealed that the high expression level of BLACAT1 was significantly associated with poor overall survival only in uterine corpus endometrial carcinoma (p = 0.002, log-rank test)." (PMID 29037201, 2017).